S100A12 (S100 calcium binding protein A12)
Diseases named in the same sentence as S100A12 in open-access papers (continued):
Sharing a sentence is not in itself a finding about the gene and the disease.
endothelial dysfunction (3 papers, 2025 to 2026). In vascular diseases, endothelial dysfunction is a systemic pathological state of the endothelium (the inner lining of blood vessels) and can be broadly defined as an imbalance between vasodilating and vasoconstricting substances produced by (or acting on) the endothelium. "Through activation of these pathways, S100A12 drives inflammatory amplification, promotes cytokine release, pyroptotic and apoptotic cell death, endothelial dysfunction, and impaired tubular repair, thereby exacerbating renal injury." (PMID 41657733, 2026). "Collectively, these results indicate S100A12 may serve functions beyond a diagnostic biomarker, also an active pathogenic mediator in SIMD, contributing to myocardial damage via inflammatory injury, oxidative stress, and endothelial dysfunction." (PMID 40926894, 2025). "Key proteins, elevated in severe cases, including SYND1, S100A12, HGF and CDCP1, reflect processes such as endothelial dysfunction, neutrophil activation, tissue remodeling and systemic inflammation." (PMID 40429886, 2025).
fungal infections (3 papers, 2024 to 2025). "S100A12 was described to function as an antimicrobial peptide for bacterial and fungal infections." (PMID 39066246, 2024).
glioma (3 papers, 2020 to 2025). A benign or malignant brain and spinal cord tumor that arises from glial cells (astrocytes, oligodendrocytes, ependymal cells). "We assumed that S100A12 was upregulated in glioma tissues, and that knockdown of S100A12 resulted in a repression of apoptosis and a elevation of proliferation of glioma cells." (PMID 32228516, 2020). "In the present study, we carried out immunohistochemical investigation of S100A12 in 81 glioma tissues to determine the expression of S100A12 in glioma cells, and evaluate the clinical significance of S100A12 in glioma patients." (PMID 32228516, 2020). "The results showed the silence of S100A12 dramatically increased apoptosis rates in both U251 and U87 glioma cells (P < 0.01)." (PMID 32228516, 2020). "Our results showed that the overexpression of S100A12 was closely related with poor prognosis of glioma patients." (PMID 32228516, 2020). "We found that S100A12 was upregulated in tissues of glioma patients and the expression was correlated to WHO stage and tumor size." (PMID 32228516, 2020). "The immunohistochemistry results showed that S100A12 positive staining mainly occurs in the cellular compartment of nuclei, and the staining of glioma tissues was significantly stronger than normal brain tissues." (PMID 32228516, 2020). "To investigate the expression of S100A12 in glioma individuals, we first analyze 81 cases of glioma tissues and 6 cases of control tissues." (PMID 32228516, 2020). "We found that S100A12 expression was significantly up-regulated in U251 and U87 glioma cell lines compared with those in A172, U373 and U118 glioma cell lines." (PMID 32228516, 2020). "To further analysis the biological behavior of S100A12 in glioma, we examined the expression of S100A12 by western blot analysis." (PMID 32228516, 2020). "In this study, silencing of S100A12 significantly down-regulated the cell viability and proliferation in two glioma cell lines." (PMID 32228516, 2020). "Further, we found that knockdown S100A12 inhibits the proliferation, migration and invasion of glioma cells through regulating cell apoptosis and EMT." (PMID 32228516, 2020). "Moreover, silencing of S100A12 also caused the up-regulation of the protein expression of cleaved caspase 3 and Bax and down-regulation of Bcl2.These results indicated that S100A12 might contribute to the proliferation and apoptosis of glioma cells." (PMID 32228516, 2020). "In this study, we found that the protein expression of S100A12 was significantly up-regulated in human glioma samples." (PMID 32228516, 2020). "We then assessed the effect of S100A12 on the apoptosis of glioma cell lines by flow cytometry assay." (PMID 32228516, 2020). "However, high stromal expression of S100A12 in hepatocellular cancer is associated with poor patient outcome, and a recent study shows that S100A12 expression in tissues of glioma patients is correlated to tumor grade and size." (PMID 34067757, 2021). "We also investigated the effect of S100A12 on glioma cells invasion and migration." (PMID 32228516, 2020). "S100A12 plays a vital role in glioma progression, and may be an important regulatory molecule for biological behaviors of glioma cell lines." (PMID 32228516, 2020). "Furthermore, knockdown of S100A12 participated in the glioma cell apoptosis, which significantly increased the percentage of apoptosis rates in U87 and U251 cell lines." (PMID 32228516, 2020). "In this study, we found that the protein expression of S100A12 was significantly increased in human glioma samples and the overexpression of S100A12 may be closely correlated with the prognosis of glioma patients." (PMID 32228516, 2020). "Our results give novel prospect that S100A12 plays a vital role in glioma progression." (PMID 32228516, 2020). "S100A12 was up-regulated in glioma samples and might contributed to the prognosis of glioma patients." (PMID 32228516, 2020). "Therefore, the aim of this study was to explore the role of S100A12 in glioma." (PMID 32228516, 2020).
glioma (continued). "However, the role of S100A12 in glioma hasn’t been fully illuminated." (PMID 32228516, 2020). "Taken together, S100A12 increased the invasion and migration of glioma cells and reversed the EMT phenotype in glioma cells." (PMID 32228516, 2020). "Moreover, silencing of S100A12 inhibits the proliferation and EMT process and promotes the apoptosis of two glioma cell lines." (PMID 32228516, 2020). "In addition, silencing of S100A12 markedly reduced the proliferation and the EMT process, whereas increased the apoptosis in two glioma cell lines, U87 and U251." (PMID 32228516, 2020). "However, the role of S100A12 in glioma has not yet been identified." (PMID 32228516, 2020). "In addition, the mechanism of the effect of S100A12 on glioma was not deep enough." (PMID 32228516, 2020).
Hyperglycemia (3 papers, 2020 to 2022). An increased concentration of glucose in the blood. "In this study, the difference in S100A12 gene expression between the HME and LME groups was probably because of factors other than oxidative stress, which was caused by hyperglycemia." (PMID 35778422, 2022). "We focussed on S100A9 and S100A12 as we found the expression of these genes to be increased by hyperglycemia during monocyte/macrophage differentiation under IFNγ stimulation." (PMID 32582175, 2020). "H3K4me1 for S100A9 and H3K4me3 for S100A12 were sustained in transient hyperglycemia, significant by paired t-test only." (PMID 32582175, 2020). "Gene expression was increased in M1 macrophages in 3 out of 4 donors for S100A9 and all donors for S100A12 in both HG as well as transient hyperglycemia compared to NG." (PMID 32582175, 2020). "Mechanistically, it was found that hyperglycemia increased the acetylation of histones which were bound to the S100A9 and S100A12 promoters in the “M1” or pro-inflammatory macrophages in processes involving SMYD3 and SET7/9 [36•]." (PMID 34081211, 2021). "Transient hyperglycemia still presented 26 and 60% of the fold change increase induced by HG for S100A9 and S100A12, respectively." (PMID 32582175, 2020). "We conclude that hyperglycemia upregulates expression of S100A9, S100A12 via epigenetic regulation and induces an activating histone code on the respective gene promoters in M1 macrophages." (PMID 32582175, 2020). "Hyperglycemia-induced changes of H3K4me1, H3K4me3, and AceH3 was similar at promoters of S100A9 and S100A12 in M1 macrophages." (PMID 32582175, 2020). "Hyperglycemia-induced effect on the activating histone modifications H3K4me1, H3K4me3, and AceH3 on promoters of both S100A9 and S100A12 was similar." (PMID 32582175, 2020). "Using Affymetrix microarray profiling and RT-qPCR we identified that hyperglycemia increased the expression of S100A9 and S100A12 in primary human macrophages." (PMID 32582175, 2020). "Hyperglycemia increased acetylation of histones bound to the promoters of S100A9 and S100A12 in M1 macrophages." (PMID 32582175, 2020). "In all three experiments expression levels of S100A9 and S100A12 were affected by glucose (indicating that the donors responded to hyperglycemia) as well as stimulatory factor compared to non-stimulated cells and solvent controls)." (PMID 32582175, 2020). "We investigated whether hyperglycemia affects the histone codes on the promoters of S100A9 and S100A12 genes." (PMID 32582175, 2020). "The highest effect of hyperglycemia was gene expression of S100A9 and S100A12, in particular in pro-inflammatory M1 macrophages which are maturated with MCSF and simultaneously stimulated with IFNγ, and for S100A8 in M0 macrophages, maturated without additional stimulation." (PMID 32582175, 2020).
influenza (3 papers, 2021 to 2023). An acute viral infection of the respiratory tract, occurring in isolated cases, in epidemics, or in pandemics; it is caused by serologically different strains of viruses (influenzaviruses) designated A, B, and C, has a 3-day incubation period, and usually lasts for 3 to 10 days. "Lei found that S100A12 was a prominent biomarker for severe influenza and that its expression tended to increase with increasing viral load." (PMID 37814484, 2023). "The elevation of S100A12 expression in severe influenza infection can be compared to that in severe bacterial infection." (PMID 34108608, 2021). "Then, S100A12 was found to be a marker for severe influenza infection, and there was an upward trend of S100A12 expression as the severity level of influenza infection increased." (PMID 34108608, 2021). "As the severity level of influenza infection increases, we can observe higher level of S100A12 expression." (PMID 34108608, 2021). "Then, using microarray data from six independent studies on influenza infection, I demonstrated that S100A12 was a marker for severity of influenza infection." (PMID 34108608, 2021). "Although small fluctuation was observed in the S100A12 expression, it stayed relatively constant throughout the whole year (p = 0.11 between day 0 of influenza infection and the next spring)." (PMID 34108608, 2021). "Then, I further examined how S100A12 expression is elevated at different severity levels of influenza infection." (PMID 34108608, 2021). "This demonstrated a step-wise increase of S100A12 expression as the severity level of influenza infection increased." (PMID 34108608, 2021). "This also validated the upward trend of S100A12 expression as the severity of influenza infection increases." (PMID 34108608, 2021). "In addition, patients with severe flu also had significantly elevated S100A12 expression compared to the moderate flu group (p = 1.91e-13)." (PMID 34108608, 2021). "Next, I examined whether S100A12 expression can be a marker for severe respiratory viral infection especially influenza infection." (PMID 34108608, 2021).
intracerebral hemorrhage (3 papers, 2019 to 2023). A cerebrovascular disorder characterized by bleeding into one or both cerebral hemispheres including the basal ganglia and the cerebral cortex. "Some previous studies have confirmed that S100A12 levels in the peripheral blood reflected the severity and poor prognosis of patients with ischemic stroke, spontaneous intracerebral hemorrhage and severe traumatic brain injury." (PMID 30548434, 2019). "In patients with intracerebral hemorrhage, a higher level of S100A12 is positively correlated with inflammation, bleeding severity, and short-term mortality, suggesting that S100A12 may be a biomarker for predicting poor outcomes of hemorrhagic stroke." (PMID 37217870, 2023). "In addition, S100A12 serum levels increase after traumatic brain injury (TBI) and intracerebral hemorrhage (ICH)." (PMID 36691064, 2023).
ischemic stroke (3 papers, 2019 to 2026). A stroke disorder caused by obstruction of blood flow to the brain, due to thrombotic (local blood clot formation) or embolic (due to a blood clot or other material traveling from another site) event. "These included genes that have been previously associated with CVD in human studies such as PTX3 (pentraxin 3) and S100A12 (EN-RAGE), as well as genes that have been associated with CVD only in animal studies such as ANXA3 and SLPI, both shown to be up-regulated in rodent models of ischemic stroke." (PMID 32780732, 2020).
lupus nephritis (3 papers, 2019 to 2022). Glomerulonephritis in the context of systemic lupus erythematosus. "SLE can increase the levels of S100A8, S100A9, and S100A12 in serum and the combination of the three proteins can be used as biomarkers for lupus nephritis caused by SLE." (PMID 35796625, 2022).
pancreatitis (3 papers, 2022 to 2024). Inflammation of the pancreas. "This study shows that the systemic inflammatory biomarkers serum calprotectin and S100A12, and α1PI as a marker of systemic antiprotease capacity, are commonly increased in Miniature Schnauzers with a diagnosis of pancreatitis." (PMID 37505833, 2023). "Serum calprotectin and S100A12 appear to be of limited utility as surrogate markers to differentiate presentations of pancreatitis in dogs." (PMID 37505833, 2023). "Interestingly, serum calprotectin (and S100A12) concentrations were also significantly lower in a study of Miniature schnauzers with pancreatitis and vomiting." (PMID 39238011, 2024). "All serum markers were increased in dogs with pancreatitis, with serum α1PI accurately separating typically from atypically presenting dogs and a similar trend for the ratio of serum concentrations of calprotectin-to-S100A12." (PMID 37505833, 2023). "Thus, further longitudinal evaluation of the serum calprotectin-to-S100A12 ratio in larger cohorts of dogs with different presentations and severities of pancreatitis and in comparison to serum CRP concentrations is warranted." (PMID 37505833, 2023). "However, serum α1-proteinase inhibitor concentrations (α1PI, a serum antiprotease), calprotectin, and S100A12 concentrations (inflammatory markers) have not been extensively evaluated in dogs with pancreatitis." (PMID 37505833, 2023).
papillary thyroid cancer (3 papers, 2020 to 2022). "For example, the expression of S100A12 was significantly upregulated in human papillary thyroid cancer, and knockdown of S100A12 significantly inhibited propagation, transfer, invasion, and cell cycle progression of cancer cells." (PMID 35909123, 2022). "In this study, we analyzed the expression of S100A12 in human papillary thyroid cancer (PTC) samples and two PTC cell lines." (PMID 32015423, 2020).
prostate carcinoma (3 papers, 2021 to 2023). A carcinoma that arises from epithelial cells of the prostate gland. "Taken together, this shows that high levels of S100A9, S100A12 and high monocyte count in blood are associated with a particularly bad outcome in patients with prostate cancer metastases." (PMID 34067757, 2021). "This is the first study showing that high blood monocyte count and high mRNA expression of S100A9 or S100A12 in PBMCs are associated with particularly poor outcome in patients with prostate cancer metastases, with monocytes providing independent prognostic information." (PMID 34067757, 2021). "More studies are needed to understand the mechanisms behind as well as the effects of the increased levels seen for circulating monocytes and expression of S100A9 and S100A12 in PBMCs in prostate cancer patients with particularly poor prognosis." (PMID 34067757, 2021). "In this prospective study, we evaluated the mRNA levels of two members of this family, S100A9 and S100A12, in peripheral blood mononuclear cells (PBMCs) in a cohort of 121 prostate cancer patients using RT-PCR." (PMID 34067757, 2021). "The aim of this prospective study was to assess the prognostic value of the inflammation markers S100A9 and S100A12 together with the monocyte count in blood samples from a cohort of 121 prostate cancer patients." (PMID 34067757, 2021). "In this prospective study, the aim was to evaluate the level distribution of S100A9 and S100A12 in peripheral blood mononuclear cells (PBMCs) and its prognostic value in prostate cancer patients." (PMID 34067757, 2021). "This protein complex is overexpressed in human bladder and prostate cancers, whereas results for S100A12 have not been clear." (PMID 35324835, 2022). "We did not confirm if the levels of S100A9, S100A12 and monocytes in blood reflected an inflammatory profile in the prostate cancer tissue, but this is not unlikely." (PMID 34067757, 2021). "There is sparse information regarding S100A12 and cancer, with no studies on S100A12 and prostate cancer to our knowledge." (PMID 34067757, 2021).
pulmonary hypertension (3 papers, 2021 to 2023). Increased pressure within the pulmonary circulation due to lung or heart disorder. "S100A12 level is elevated in pulmonary hypertension patients, so it is positively associated with mortality." (PMID 37217870, 2023). "S100A12 level is also elevated in pulmonary hypertension patients and is positively associated with mortality." (PMID 37217870, 2023). "S100A12 may worsen VSMC proliferation and survival or endothelial dysfunction in pulmonary hypertension via MAPK or NF-κB signaling pathways, and even lead to increased mortality." (PMID 37217870, 2023).
pulmonary TB (3 papers, 2016 to 2025). "Contrary, RAGE is protective against the development of pulmonary TB in mouse models in line with reduction of antimicrobial activity in human macrophages upon TLR2/1 ligand activation by S100A12 knockdown." (PMID 32849645, 2020).
septic shock (3 papers, 2019 to 2024). Shock caused by infection; frequently caused by gram negative bacteria, although some cases have been caused by other bacteria, viruses, fungi, and protozoa; characterized by fever, chills, tachycardia, tachypnea, and hypotension. "S100A12 is a calcium-binding protein expressed in the cytoplasm of neutrophils and also found in monocytes and lymphocytes.The plasma level of S100A12 in patients with septic shock have been reported to be higher than in healthy volunteers." (PMID 36439140, 2022). "We measured plasma levels of two DAMPs, S100A8/S100A9 and S100A12 during the first 24 h of admission of septic shock patients." (PMID 31666644, 2019).
Shock (3 papers, 2021 to 2023). The state in which profound and widespread reduction of effective tissue perfusion leads first to reversible, and then if prolonged, to irreversible cellular injury. "UPP1, S100A9, KIF1B, S100A12, SLC26A8 emerge remarkable diagnostic performance in pediatric septic shock and involved in immune cells infiltration." (PMID 36439140, 2022). "Interestingly, the S100A12 expression was significantly decreased from T1 to T2 (p = 0.002) and also from T2 to T3 (p = 0.023) for patients with septic shock." (PMID 34108608, 2021).
thoracic aortic aneurysm (3 papers, 2014 to 2024). An aneurysm formed in the wall of the proximal portion of the descending aorta proceeding from the arch of the aorta. "Increased levels of S100A12 have been significantly associated with increased cell death, tissue damage, and thoracic aortic aneurysm." (PMID 25093596, 2014). "Many S100 family proteins, such as S100A8, S100A9, and S100A12, play a key role in thoracic aortic aneurysms and other cardiovascular diseases 40-42." (PMID 38164183, 2024). "Follow-up researches find that S100A12 is markedly expressed in the tissue and serum of patients with thoracic aortic aneurysms and dissections." (PMID 37217870, 2023). "Therefore, elevated S100A12 level could play a vital role in predicting preoperative complications in patients with thoracic aortic aneurysms and dissections." (PMID 37217870, 2023).